hsa-mir-8069-1 (hsa-mir-8069-1 )
Synonyms: MIR8069-1
Gene: MicroRNA gene on chromosome 21 (6,859,171 to 6,859,256, forward strand). Ensembl gene ENSG00000284550.
Homologues: Paralogues in human: MIR8069 (100% identical).